ANPEP (alanyl aminopeptidase, membrane)
Description:
Broad specificity aminopeptidase which plays a role in the final digestion of peptides generated from hydrolysis of proteins by gastric and pancreatic proteases. Also involved in the processing of various peptides including peptide hormones, such as angiotensin III and IV, neuropeptides, and chemokines. May also be involved the cleavage of peptides bound to major histocompatibility complex class II molecules of antigen presenting cells. May have a role in angiogenesis and promote cholesterol crystallization. May have a role in amino acid transport by acting as binding partner of amino acid transporter SLC6A19 and regulating its activity (By similarity). (Microbial infection) Acts as a receptor for human coronavirus 229E/HCoV-229E. In case of human coronavirus 229E (HCoV-229E) infection, serves as receptor for HCoV-229E spike glycoprotein. (Microbial infection) Mediates as well Human cytomegalovirus (HCMV) infection.
Synonyms: AP-N; hAPN; AP-M; CD13; APN; PEPN; LAP1; gp150; p150
Tractability: Small molecule: a drug acting on it is in phase 2 or 3 trials; a structure with a bound ligand is known; a high-quality ligand is known; it belongs to a druggable protein family. Antibody: UniProt places it where antibodies can reach, with high confidence; its Gene Ontology location is reachable by antibodies, with high confidence; UniProt predicts a signal peptide or a membrane-spanning region; the Human Protein Atlas places it where antibodies can reach. PROTAC: its protein half-life has been measured; a small molecule that binds it is known.
Target class: Protease; Enzyme; Metallo protease; Metallo protease MAE clan; Metallo protease M1 family
Chemical probes: CHEMBL1077583
Gene: Protein-coding gene on chromosome 15 (89,784,875 to 89,815,401, reverse strand). Ensembl gene ENSG00000166825.
Subcellular location: Cell membrane
Subcellular location (Human Protein Atlas): Plasma membrane
Pathways (Reactome):
Immune System: Neutrophil degranulation
Metabolism of proteins: Metabolism of Angiotensinogen to Angiotensins
Gene Ontology:
Molecular function: alanyl aminopeptidase activity; aminopeptidase activity; metalloaminopeptidase activity; metallopeptidase activity; signaling receptor activity; zinc ion binding
Biological process: angiotensin maturation; peptide catabolic process; proteolysis
Cellular component: endoplasmic reticulum-Golgi intermediate compartment; extracellular exosome; extracellular region; lysosomal membrane; plasma membrane; secretory granule membrane; external side of plasma membrane
Genetic constraint (gnomAD): Loss-of-function variants: 70 observed, 121.14 expected, observed/expected ratio (o/e) 0.58, 90% interval 0.48 to 0.7. The upper end of that interval is the gene's LOEUF score, 0.7, which puts it in group 2 of 6, group 1 being the genes least tolerant of losing a copy. Missense variants: 1,184 observed, 1,321.5 expected, observed/expected ratio (o/e) 0.9, 90% interval 0.85 to 0.94. Synonymous variants: 548 observed, 550.99 expected, observed/expected ratio (o/e) 0.99, 90% interval 0.93 to 1.07.
Homologues: Orthologues: chimpanzee ANPEP (99% identical), macaque ANPEP (95% identical), pig ANPEP (79% identical), rat Anpep (78% identical), dog ANPEP (78% identical), mouse Anpep (77% identical), guinea pig ANPEP (75% identical), zebrafish anpepb.1 (59% identical), rabbit ANPEP (59% identical), tropical clawed frog anpep (59% identical), zebrafish anpepa (56% identical), zebrafish anpepb.2 (55% identical), and 14 more. Paralogues in human: LVRN (35% identical), ENPEP (32% identical), ERAP1 (31% identical), ERAP2 (31% identical), LNPEP (30% identical), NPEPPS (29% identical), TRHDE (26% identical), RNPEP (14% identical), RNPEPL1 (13% identical), AOPEP (12% identical), LTA4H (11% identical).
Diseases named in the same sentence as ANPEP in open-access papers:
ANPEP is named in the same sentence as 270 diseases in open-access papers, as found by Europe PMC text mining. Sharing a sentence is not in itself a finding about the gene and the disease. The quoted sentences say what the papers report.
leukemia (38 papers, 2007 to 2025). A malignant (clonal) hematologic disorder, involving hematopoietic stem cells and characterized by the presence of primitive or atypical myeloid or lymphoid cells in the bone marrow and the blood. "The non-leukemic nature of the three monocyte/macrophage clusters was confirmed by low expression of leukemia myeloid markers (ITGAM, ANPEP, CD33)." (PMID 37798266, 2023).
liver cancer (37 papers, 2013 to 2026). An epithelial or non-epithelial malignant neoplasm that arises from the liver. "Chronic stress-induced glucocorticoids promoted aminopeptidase N (ANPEP) expression and subsequent reprogramming of amino acid metabolism, leading to increased liver cancer growth and metastasis." (PMID 41697737, 2026). "Knockdown of ANPEP blocked chronic stress-induced liver cancer progression." (PMID 41329521, 2025). "Moreover, prolonged MB109 treatment suppressed the expression of five prominent liver cancer stem cell (LCSC) markers, including CD44, CD90, AFP, GPC3 and ANPEP." (PMID 27650540, 2016).
breast carcinoma (31 papers, 2013 to 2025). "Six of the genes (CASP1, CCL2, ADGRE5, IL3RA, RSPO1, and STAB1) are co‐expressed with the CH25H gene in both cancers, while two genes (ANPEP in breast cancer and CCL8 in prostate cancer) are exclusively co‐expressed with the CH25H gene in one of the tumors." (PMID 41159143, 2025). "Also, ANPEP is part of the mesenchymal markers of Mouse mammary carcinoma cell line induced to EMT with TGF-β." (PMID 32850411, 2020). "The ANPEP gene regulates the epithelial–mesenchymal transition (EMT) pathway and is responsible for apoptosis in breast cancer cell lines." (PMID 41226241, 2025).
prostate carcinoma (28 papers, 2009 to 2025). A carcinoma that arises from epithelial cells of the prostate gland. "High levels of CD13/ANPEP expression have been observed in a variety of solid tumors; additionally, CD13 has been shown to be associated with malignant activity in colon and prostate cancers." (PMID 35884586, 2022). "However, reduced ANPEP expression and hypermethylation in prostate cancer tissues are linked to recurrence risk." (PMID 41465326, 2025). "Consistent with previous reports that low expression and hypermethylation of ANPEP were correlated inversely with survival in prostate cancer." (PMID 34633989, 2021). "In prostate cancer patients, low expression and aberrant promoter hypermethylation of ANPEP have been considered as a new independent adverse prognostic factor for patients." (PMID 34633989, 2021). "Also, one of the metabolic targets of icatibant is ANPEP, which is a prognostic marker for prostate cancer." (PMID 37495601, 2023). "Moreover, previous finding regarding silenced ANPEP in prostate cancer have revealed that hypermethylation in the promoter region of ANPEP correlated inversely with its expression." (PMID 36748835, 2023). "A previous study showed that ANPEP was downregulated in prostate cancer (PC)." (PMID 29850522, 2018).
melanoma (26 papers, 2004 to 2025). A malignant, usually aggressive tumor composed of atypical, neoplastic melanocytes. "The expression of ANPEP was high associated with DNA methylation status of the ANPEP promoter in melanoma cells." (PMID 34633989, 2021). "It remains to be elucidated whether high expression of CD13/ANPEP is associated with propensity of melanoma cells to exhibit ligand-independent EPHA2 signaling." (PMID 29048432, 2017). "Inhibition of DNA methyltransferase increased ANPEP expression and reduced APN-dependent migration of melanoma cells." (PMID 34633989, 2021). "Nevertheless, these indicated the expression axis ANPEP/SDC1/integrin β4 existed in melanoma cells, which was downregulated by anchorage independence." (PMID 32756007, 2020). "We examined the expression of ANPEP in adherent, suspended, and reattached melanoma cells by qPCR and flow cytometry." (PMID 32756007, 2020). "In this study, we found that anchorage-independence of melanoma cells downregulated aminopeptidase N (ANPEP) expression, which downregulated SDC1 expression, thus further downregulated integrin β4 expression." (PMID 32756007, 2020). "Our previous microarray data (GSE42876 and GSE61671) showed downregulation of ANPEP gene expression in suspended melanoma cells and reattached melanoma cells." (PMID 32756007, 2020). "ShRNAs transfection reduced ANPEP expression levels (53% and 39% for shANPEP_a and shANPEP_b, respectively) in melanoma cells." (PMID 32756007, 2020). "This was consistent with reported literatures that ANPEP played role in melanoma cell invasion." (PMID 32756007, 2020). "This suggested ANPEP might play a role as tumor suppressor in melanoma cells under detachment stress." (PMID 32756007, 2020). "Although it was demonstrated that ANPEP, SDC1, and integrin β4 were associated with vessel formation/angiogenesis, our results suggested the sequential expression of ANPEP/SDC1/integrin β4 through PKCδ activation determined the vasculogenic phenotype of melanoma cells." (PMID 32756007, 2020). "We hypothesized that the regulation of ANPEP, SDC1, and integrin β4 expression might associate with loss of vasculogenic phenotype upon suspension of melanoma cells." (PMID 32756007, 2020). "This suggested downregulation of ANPEP in suspended melanoma cells would promote tumor malignancy." (PMID 32756007, 2020). "ANPEP is involved in melanoma angiogenesis and in melanoma cell invasion." (PMID 31142788, 2019). "Targeting CD13/ANPEP by a blocking antibody induced apoptosis in both parental A375- and BRAFi-resistant daughter cells as well as in melanoma cells with intrinsic BRAFi resistance and led to dephosphorylation of EPHA2 on S897, previously demonstrated to cause inhibition of the migratory capacity." (PMID 29048432, 2017). "However, we observed that the reduced level of ANPEP promoted melanoma tumor growth." (PMID 32756007, 2020). "ANPEP is also an important mediator of resistance to inhibition of BRAF, one of the most aggressive oncogenes found in melanoma which modulates angiogenesis." (PMID 31142788, 2019). "For the first time, we show that CD13/ANPEP and FLI1 overexpression can mediate resistance to BRAFi in melanoma cells." (PMID 29048432, 2017). "This is the first report presenting CD13/ANPEP and FLI1 as important mediators of resistance to BRAF inhibition with potential as drug targets in BRAFi refractory melanoma." (PMID 29048432, 2017). "Aminopeptidase N (ANPEP or CD13) was a specificity aminopeptidase which had an important role in angiogenesis and participated in drug resistance via regulating ephrine receptor A2 in melanoma cells." (PMID 34633989, 2021). "Comparing our previous microarray data (GSE42876 and GSE61671) with the result of current proteomic analysis, the positive and strong correlation that both ANPEP and CAV1 gene products were downregulated in suspended melanoma cells and reattached melanoma cells." (PMID 32756007, 2020).
viral infection (23 papers, 2017 to 2025). "The CD163, ANPEP, DNAJC14, and ANTXR1 knockout pigs proved resistant to viral infections." (PMID 41465565, 2025). "While both ANPEP and DPP4 are already known as a target receptors for other coronaviruses (human coronavirus 229E, swine epidemic diarrhea virus, canine coronavirus, feline coronavirus, for ANPEP and MERS-CoV for DPP4), the relationship between ENPEP and viral infection is not yet known." (PMID 32759645, 2020).
colon carcinoma (21 papers, 2004 to 2023). "Similarly, a detailed analysis of genes downregulated in tumor samples resulted in the identification of protease genes including MMP28, ANPEP, ADAMTS1 and ADAMTS15, previously known to be repressed in colon carcinoma or in other tumor types." (PMID 24243807, 2013).
ovarian carcinoma (21 papers, 2004 to 2025). A malignant neoplasm originating from the surface ovarian epithelium. "ANPEP thus exhibits context-dependent roles (e.g., pro-tumorigenic in most cancers but tumor-suppressive in specific ovarian cancer models)." (PMID 41465326, 2025). "Except for ANPEP, also known as CD13, that was shown to be associated with ovarian cancer growth, the functions of all the other markers during development of ovarian cancer are largely unknown and worthwhile for future investigation." (PMID 34459128, 2021). "Particularly, we examined if ANPEP (from EC2), CASP14 and CLEC2B (from EC3), CADM3 and NRBP2 (from EC4), and SPC25, ESCO2, and GTSE1 (from EC5) are responsible for ovarian cancer cell proliferation by the cell viability assay." (PMID 34459128, 2021).
non-small cell lung carcinoma (18 papers, 2008 to 2024). A group of at least three distinct histological types of lung cancer, including non-small cell squamous cell carcinoma, adenocarcinoma, and large cell carcinoma. "In non-small cell lung cancer, in tumor-associated endothelial cells, high ANPEP levels are in association with angiogenesis and poor prognosis, as determined by microvessel density and/or VEGF expression." (PMID 32179814, 2020).
COVID-19 (16 papers, 2020 to 2025). A disease caused by infection with severe acute respiratory syndrome coronavirus 2. "In our analysis, ANPEP expression was most abundant in cluster 2, the cluster characterized by the highest expression of genes linked to neutrophil immaturity, aligning with our analysis of COVID-19 datasets." (PMID 40168094, 2025). "Additionally, the ANPEP gene (also known as CD13) has been associated with gastrointestinal system involvement in COVID-19." (PMID 38813031, 2023). "Specifically, single-cell RNA-Seq analysis of lung samples and peripheral blood showed elevation of ANPEP expression at the transcription level in COVID-19 samples." (PMID 40168094, 2025). "We found similar results, showing that COVID-19 patients with higher ANPEP expression levels in immune cells had more severe disease based on the WHO severity score for COVID-19." (PMID 40168094, 2025). "In the current study, we observed that the expression of the ANPEP gene was lower in pediatric patients with COVID-19." (PMID 38813031, 2023). "ANPEP and ACE are two genes that have been implicated in COVID-19 due to their involvement in the renin-angiotensin-aldosterone system (RAS)." (PMID 38813031, 2023). "The downregulation of ACE2 (COVID-19, SARS) and ANPEP (HCoV-229E) viral receptors wascorrelated with loss of club and ciliated cells in Th2 high asthma." (PMID 34198852, 2021). "Using a gene set associated with neutrophil immaturity, we identified immature neutrophils in the lungs and peripheral immune cells of patients with COVID-19, particularly those with severe disease, where these cells were more prevalent and showed high ANPEP expression." (PMID 40168094, 2025). "Indeed, ANPEP was upregulated in cells collected from the airway specimens of patients with COVID-19 compared with healthy controls, specifically in patients with moderate disease." (PMID 40168094, 2025). "Since ANPEP was highly expressed on various cell types in the lung, we then determined whether cellular ANPEP expression levels were altered in patients with COVID-19." (PMID 40168094, 2025). "In light of the importance of neutrophil dysfunction in the pathophysiology of COVID-19, especially in severe cases, we analyzed the expression level of neutrophil ANPEP in patients with COVID-19 who were divided into 2 populations, ANPEP-high (above the median) versus ANPEP-low (below the median)." (PMID 40168094, 2025). "This suggests that besides its direct proinflammatory roles, increased bradykinin levels may indirectly contribute to inflammation by repressing ANPEP activity in COVID-19 patients." (PMID 34000623, 2021). "Thus, the ACE and ANPEP genes may contribute to the severity and progression of COVID-19 by influencing the virus’s ability to enter human cells and modulating the response of the RAS to the infection." (PMID 38813031, 2023). "Finally, we found reduced levels of aminopeptidase N (ANPEP) in lungs of COVID-19 patients." (PMID 34000623, 2021). "Specifically, we have emphasized the significance of the ANPEP and IGF2R genes, which play unique roles in the progression of COVID-19 from the initiating phase to the propagating phase." (PMID 38813031, 2023). "The study results indicated that the expression of critical biogenomic markers, such as the first-phase (ACE2 and ANPEP) and second-phase (EGFR and IGF2R) receptor genes, was crucial in the genesis of mild clinical presentations of pediatric COVID-19." (PMID 38813031, 2023). "In conclusion, the expression of critical biogenomic markers, including the ACE2, ANPEP, EGFR, and IGF2R genes, plays a significant role in the development of mild clinical presentations in pediatric COVID-19 cases." (PMID 38813031, 2023). "Recent studies have demonstrated that the S1 domain of COVID-19 S protein potentially interacts with DPP4 when the virus enter cells of the respiratory tract; Alanyl aminopeptidase (ANPEP), also named as CD13, is a receptor for human coronavirus-229E." (PMID 35464443, 2022).
COVID-19 (continued). "We explored the association of coronavirus receptors with GBM and identified ANPEP and ENPEP as potential biomarkers and therapies for COVID-19 and GBM." (PMID 35464443, 2022). "Both higher levels of ANPEP in monocytes and granulocytes and higher levels of DPP4 in T cells and dendritic cells were observed in COVID-19 patients compared with HC." (PMID 34349096, 2021). "We find the gut as the putative hotspot of COVID-19, where a maturation correlated transcriptional signature is shared in small intestine enterocytes among coronavirus receptors (ACE2, DPP4, ANPEP)." (PMID 32463365, 2020). "The Cox regression analyses suggested that 9 prognostic genes (ANPEP, OAS1, SCGB1A1, HLA‐A, NPPB, FGB, CCL2, TLR4, and SERPINE1) might act critical roles in the treatment of UCEC/COVID-19." (PMID 36969077, 2023). "Particularly in adult patients, screening for ANPEP and IGF2R gene expressions could be valuable for predicting the severity of the clinical course of COVID-19." (PMID 38813031, 2023). "The interrelationship between the ANPEP and ACE genes might impede the progression of COVID-19 from the initiation phase to the propagating phase in pediatric patients." (PMID 38813031, 2023). "Then, regression analyses indicated that 9 prognostic genes (including ANPEP, OAS1, SCGB1A1, HLA‐A, NPPB, FGB, CCL2, TLR4, and SERPINE1) might play important roles in quercetin for treating UCEC/COVID-19." (PMID 36969077, 2023). "Our work explores for the first time the association of coronavirus receptors with GBM and suggests ANPEP and ENPEP as potential therapeutic targets of GBM irrespective of COVID-19." (PMID 35464443, 2022). "Notably, both low ANPEP gene expression levels and mild clinical disease courses were common features in pediatric COVID-19 patients and in adult patients without gastrointestinal involvement." (PMID 38813031, 2023). "The results of the current study support the hypothesis that the mild clinical presentations of pediatric COVID-19 are driven by the expression of critical biogenomic markers, specifically the first-phase receptor genes (ACE2 and ANPEP) and second-phase receptor genes (EGFR and IGF2R)." (PMID 38813031, 2023).
Hypertension (14 papers, 2010 to 2023). The presence of chronic increased pressure in the systemic arterial system. "In addition, increased mRNA levels of aminopeptidase N (ANPEP) are inversely associated with hypertension, angiogenesis, and inflammation; this may explain the beneficial role of regular intake of kimchi on lipid profile and blood pressure." (PMID 36768984, 2023).